TUBGCP4 (tubulin gamma complex component 4)
Description:
Component of the gamma-tubulin ring complex (gTuRC) which mediates microtubule nucleation. The gTuRC regulates the minus-end nucleation of alpha-beta tubulin heterodimers that grow into microtubule protafilaments, a critical step in centrosome duplication and spindle formation.
Synonyms: GCP-4; 76P; GCP4; FLJ14797; Grip76; MCCRP3
Tractability: Small molecule: a structure with a bound ligand is known. PROTAC: ubiquitination databases record sites on it; its protein half-life has been measured.
Gene: Protein-coding gene on chromosome 15 (43,369,221 to 43,409,771, forward strand). Ensembl gene ENSG00000137822.
Subcellular location: Cytoplasm, cytoskeleton, microtubule organizing center, centrosome
Subcellular location (Human Protein Atlas): Centrosome
Pathways (Reactome):
Cell Cycle: Recruitment of NuMA to mitotic centrosomes; Recruitment of mitotic centrosome proteins and complexes
Gene Ontology:
Molecular function: protein binding; gamma-tubulin binding; microtubule minus-end binding; structural constituent of cytoskeleton
Biological process: meiotic cell cycle; microtubule nucleation; mitotic cell cycle; protein-containing complex assembly; spindle assembly; microtubule cytoskeleton organization
Cellular component: centrosome; membrane; recycling endosome; cytosol; gamma-tubulin complex; gamma-tubulin ring complex; microtubule cytoskeleton; microtubule organizing center; spindle pole
Genetic constraint (gnomAD): Loss-of-function variants: 48 observed, 85.97 expected, observed/expected ratio (o/e) 0.56, 90% interval 0.44 to 0.71. The upper end of that interval is the gene's LOEUF score, 0.71, which puts it in group 2 of 6, group 1 being the genes least tolerant of losing a copy. Missense variants: 562 observed, 790.36 expected, observed/expected ratio (o/e) 0.71, 90% interval 0.66 to 0.76. Synonymous variants: 284 observed, 307.44 expected, observed/expected ratio (o/e) 0.92, 90% interval 0.84 to 1.02.
Homologues: Orthologues: chimpanzee TUBGCP4 (99% identical), macaque TUBGCP4 (99% identical), dog TUBGCP4 (99% identical), rat Tubgcp4 (98% identical), mouse Tubgcp4 (98% identical), rabbit TUBGCP4 (98% identical), guinea pig TUBGCP4 (98% identical), pig TUBGCP4 (97% identical), tropical clawed frog tubgcp4 (89% identical), zebrafish tubgcp4 (89% identical), Drosophila melanogaster Grip75 (29% identical), Drosophila melanogaster t-Grip128 (20% identical). Paralogues in human: TUBGCP6 (21% identical), TUBGCP2 (19% identical), TUBGCP3 (17% identical), TUBGCP5 (16% identical).
Diseases named in the same sentence as TUBGCP4 in open-access papers:
TUBGCP4 is named in the same sentence as 16 diseases in open-access papers, as found by Europe PMC text mining. Sharing a sentence is not in itself a finding about the gene and the disease. The quoted sentences say what the papers report.
microcephaly (8 papers, 2016 to 2025). A congenital or acquired developmental disorder in which the circumference of the head is smaller than normal for the person's age and sex. "Genetic tests revealed mutations in the TUBGCP4 gene, leading to a diagnosis of microcephaly and chorioretinopathy." (PMID 37568951, 2023). "The head size of heterozygous mice, measured by X-ray imaging of bones, was smaller than that of their wild-type littermates, an effect mimicking TUBGCP4 mutant autosomal-recessive microcephaly in humans." (PMID 31209365, 2020). "Gamma-complex component genes (TUBGCP4, TUBGCP5, and TUBGCP6) are critical in neuronal progenitor proliferation, and its variants cause cell proliferation defects and increased apoptosis, which have been reported to be associated with microcephaly." (PMID 40017707, 2025). "Autosomal recessive forms of microcephaly with chorioretinopathy are caused by mutations of the genes of the master regulator of centriole duplication, the PLK4 kinase (MCCRP2, MIM 616171), and their substrates TUBGCP4 (MCCRP3, MIM 616335) and TUBGCP6 (MCCRP1, MIM 251270)." (PMID 27099632, 2016).
hepatocellular carcinoma (1 paper, 2022). A malignant tumor that arises from hepatocytes. "We aim to investigate the expression and clinical significance of the tubulin gamma complex-associated protein 4 (TUBGCP4) in hepatocellular carcinoma (HCC)." (PMID 36530949, 2022).
mantle cell lymphoma (1 paper, 2022). Mantle cell lymphoma is a rare form of malignant non-Hodgkin lymphoma affecting B lymphocytes in the lymph nodes in a region called the ``mantle zone''. "In the study of mantle cell lymphoma, TUBGCP4 expression was found to be associated with both tetraploidization and high levels of centrosome aberrations." (PMID 36530949, 2022). "It has been found that TUBGCP4 protein is abnormally expressed in ovarian epithelial carcinoma, mantle cell lymphoma, and myeloma and is closely related to tumor cell growth and metastasis." (PMID 36530949, 2022).
cancer (2 papers, 2013 to 2022). A tumor composed of atypical neoplastic, often pleomorphic cells that invade other tissues. "Subsequently, to further explore the mechanism of TUBGCP4, we constructed a hypothetical protein network and found that TUBGCP4 plays a role in promoting cancer cell growth and proliferation." (PMID 36530949, 2022). "In recent years, some studies have shown that TUBGCP4 is overexpressed in various malignant tumors and considered to be an oncogene." (PMID 36530949, 2022). "The abnormal expression of TUBGCP4 can lead to many diseases, especially malignant tumors." (PMID 36530949, 2022). "Therefore, as a component of the γ-tubulin ring complex, the analysis of the expression of TUBGCP4 may be helpful to analyze the centrosome aberration of malignant tumors, and they are of great significance to the prognosis of various malignant tumors." (PMID 36530949, 2022).
tumor (1 paper, 2022). "We also found that the postoperative tumor-free survival rate of HCC patients in the TUBGCP4 positive group was significantly higher than that in the negative group (P = 0.003)." (PMID 36530949, 2022). "Moreover, we found that the total postoperative survival time and tumor-free survival time in the TUBGCP4 positive group were significantly longer than that of the TUBGCP4 negative group." (PMID 36530949, 2022). "Since, they are the three important tumor-related pathways, which supports that TUBGCP4 might be involved in the occurrence and development of HCC." (PMID 36530949, 2022). "Further, survival analysis showed that the overall survival time and tumor-free survival time in the TUBGCP4 positive group were significantly higher than those of the negative group (P < 0.05), indicating that the positive expression of TUBGCP4 was related to a better prognosis of HCC patients." (PMID 36530949, 2022).
TUBGCP4 also shares sentences with these, for which no sentence is quoted: Chorioretinal atrophy (1 paper); cone-rod retinal dystrophy (1); epilepsy (1); infection (1); liver cirrhosis (1); microphthalmia (1); optic nerve hypoplasia (1); retinal degeneration (1); retinopathy (1); status epilepticus (1); vascular tumor (1).